DDIT4 (DNA damage inducible transcript 4)
Diseases named in the same sentence as DDIT4 in open-access papers (continued):
Sharing a sentence is not in itself a finding about the gene and the disease.
leukemia (continued). "Although it has been reported that high DDIT4 expression is related to a poor prognosis in several types of solid tumors and leukemia, the mechanism and its role in leukemogenesis and leukemia cell stemness have not been elucidated yet." (PMID 40621878, 2025). "Our findings reveal that DDIT4 upregulates HOXA expression in AML1‐ETO‐positive leukemia cells, suggesting that DDIT4‐high cells may represent a distinct chemoresistant subpopulation within AML1‐ETO leukemia." (PMID 40621878, 2025). "In conclusion, we show that lovastatin blocks leukemia proliferation in part through activation of cholesterol biosynthesis and induction of the transcription factor KLF2, capable of suppression the MAPKinase pathway, likely through downregulation of FAM83A and DDIT4." (PMID 37016335, 2023).
triple-negative breast carcinoma (7 papers, 2018 to 2025). An invasive breast carcinoma which is negative for expression of estrogen receptor (ER), progesterone receptor (PR), and human epidermal growth factor receptor 2 (HER2). "In high-grade triple-negative breast cancers, DDIT4 is also associated with a poor prognosis in human patients." (PMID 33075093, 2020). "Knocking down DDIT4 significantly inhibits the tumor progression of triple-negative breast cancer both in vitro and in vivo, and inhibiting DDIT4 can enhance the efficacy of paclitaxel in patients with triple-negative breast cancer." (PMID 41169393, 2025). "DDIT4 expression is an independent prognostic factor for triple-negative breast cancer resistant to neoadjuvant chemotherapy." (PMID 29976242, 2018). "DDIT4 participates in the regulation of autophagy in triple-negative breast cancer." (PMID 41169393, 2025).
bladder urothelial carcinoma (6 papers, 2018 to 2025). "Recently, it was reported that the inhibition of DDIT4 expression sensitizes bladder urothelial carcinoma to paclitaxel by inhibiting the DDIT4-EEF2K-autophagy axis." (PMID 37391802, 2023). "Inhibition of DNA damage inducible transcript 4 (DDIT4) in bladder urothelial carcinoma renders the cancer cells more sensitive to paclitaxel by inhibiting autophagy." (PMID 33748143, 2021). "Moreover, DDIT4 was suggested to facilitate bladder urothelial carcinoma (BUC) progression and antagonized REDD1, thereby sensitizing BUC cells to paclitaxel." (PMID 39593172, 2024).
melanoma (6 papers, 2021 to 2025). A malignant, usually aggressive tumor composed of atypical, neoplastic melanocytes. "Overexpression of DDIT4 induced by serum starvation inhibits the transcription activity of mTORC1, thereby abrogating the oncogenic potential of melanoma cells." (PMID 40584831, 2025). "To examine the functional role of DDIT4 in autophagy inducer sensitizing melanoma cells to etoposide, we transfected three DDIT4 siRNAs (si-DDIT4) into A375 and SK-MEL-28 cells treated with etoposide, respectively." (PMID 36289218, 2022). "Taken together, our results suggest that melanoma cells may be more sensitive to etoposide when present with an autophagy inducer, and this pattern may be mediated through DDIT4." (PMID 36289218, 2022).
Cachexia (5 papers, 2021 to 2025). Severe weight loss, wasting of muscle, loss of appetite, and general debility related to a chronic disease. "Downregulation of Ddit4 activates mTORC1 and protects against muscle loss in atrophy and cachexia conditions." (PMID 40641155, 2025). "The expression of Ddit4 was significantly different across each cachexia model, and genes biologically related to Ddit4 were also significantly different between the muscles of normal and cachectic mice." (PMID 34175899, 2021). "Not as expected, unlike in cancer cachexia models, Ddit4 showed a mild upregulation in the muscles in denervated and fasting models but not significantly altered in other muscle atrophy models such as immobilization, Huntingdon disease, and rapamycin-treated mice." (PMID 34175899, 2021).
head and neck squamous cell carcinoma (5 papers, 2012 to 2025). A squamous cell carcinoma that arises from any of the following anatomic sites: lip and oral cavity, nasal cavity, paranasal sinuses, pharynx, larynx, and salivary glands. "The overexpression of RBM33 in human head and neck squamous cell carcinoma (HNSCC) cells has been observed to facilitate the development of HNSCC tumors by enhancing the stability of DDIT4 in a manner that is dependent on m6A modification." (PMID 39524539, 2023). "Functionally, RBM33 is indispensable for the progression of head and neck squamous cell carcinoma (HNSCC): by recruiting ALKBH5 to demethylate and stabilize DDIT4 mRNA, RBM33 promotes autophagy and thereby drives tumorigenesis." (PMID 41562066, 2025).
liver cancer (5 papers, 2010 to 2025). An epithelial or non-epithelial malignant neoplasm that arises from the liver. "Specifically, four HRGs, decorin (DCN), DNA damage inducible transcript 4 (DDIT4), protein kinase C alpha (PRKCA), and N-myc downstream regulates gene-1 (NDRG1), were included in the hypoxic risk model for liver cancer that the researchers created." (PMID 38911968, 2024). "Such significant inverse correlation between DDIT4 mRNA levels and miR-221 expression has been observed in a mouse model of liver cancer as well." (PMID 32878239, 2020). "More recently, it has been reported that the treatment with LNA-modified miR-221 inhibitors reduces the growth of liver cancer cells over-expressing miR-221/222 in vitro by targeting a DNA damage-inducible transcript 4 (DDIT4), a modulator of the mTOR pathway." (PMID 23479461, 2013).
liver fibrosis (5 papers, 2021 to 2025). "In non-alcoholic fatty liver disease, liver fibrosis, methionine-choline-deficient diet induced steatotic liver injury, bile duct ligation surgery induced cholestatic liver injury, and in CCl4 injection induced hepatotoxic injury, abnormal increase in DDIT4 expression." (PMID 39564122, 2024). "In the BDL model of liver injury, DDIT4 knockdown similarly dampened ROS production, mitigated liver injury, weakened hepatic inflammation, and assuaged liver fibrosis." (PMID 34310076, 2021).
Sepsis (5 papers, 2019 to 2024). Sepsis is defined as life-threatening organ dysfunction caused by a dysregulated host response to infection. "Finally, increased expressions of DNA Damage Inducible Transcript 4 (DDIT4) gene had been associated with higher risks of mortality in sepsis patients." (PMID 32859206, 2020). "Interestingly, several of the genes linked to glucocorticoid signaling (Arl4d, Cdkn1a, Ddit4, Fkbp5, Gjb6, Il6ra, Klf15, Nfkbia, Rhob, Sdc4, Sgk1, Sult1a1, Tob2, Wipf3) and apoptotic process were still upregulated 4 days post-sepsis." (PMID 31278440, 2019). "Among the upregulated DEGs in E-SEP compared to Y-SEP, we observed inflammation-associated genes, such as FOSB, DUSP1, and JUNB, and aging-associated genes, such as IFN-stimulated genes DDIT4 and DUSP2, thereby indicating an overactive inflammatory response of cDCs in elderly patients with sepsis." (PMID 38909272, 2024). "The boxplot revealed 26 differentially expressed genes between the sepsis-induced ALI and control samples: Ncf2, Slc2a6, Cd44, Txnip, Slc2a1, Ubc, Hspb1, Zfp36, Arntl, Ddit4, Tnfaip3, Txnrd1, Mt1, Hmox1, Gch1, Gclc, Stat3, Egfr, Hif1a, Bach1, Socs1, Dusp1, Cdkn1a, Fth1, Steap3, and Alox12." (PMID 37081490, 2023).
tuberous sclerosis (5 papers, 2009 to 2023). Hereditary disease characterized by seizures, intellectual disability, developmental delay, and skin and ocular lesions. "DDIT4 positively regulates the activity of the Tuberous Sclerosis (TSC) complex (TSC1, TSC2 and TBC1D7), which in turn acts as a crucial negative regulator for the mTORC1 activity." (PMID 36674750, 2023). "Recent data from Ellisen and colleagues suggest that a primary Ddit4 mechanism of action is to competitively bind inhibitory 14-3-3 proteins that otherwise bind to the Tsc2 protein, part of the tuberous sclerosis complex that inhibits Akt/Frap1 signaling when Tsc2 is unbound." (PMID 19370158, 2009). "This could be explained by increasing the expression of DNA-damage-inducible transcript 4 (DDIT4), which can activate tuberous sclerosis 2, and decreasing the expression of Akt, both of which result in inhibiting the expression of mTOR." (PMID 32455017, 2020).
ataxia telangiectasia (4 papers, 2021 to 2024). Ataxia-telangiectasia is the association of severe combined immunodeficiency (affecting mainly the humoral immune response) with progressive cerebellar ataxia. "A study reported that HDAC4 increases DDIT4 transcription by modulating HIF-1 activation in ataxia-telangiectasia, but further investigation is needed to understand how HDAC4 regulates DDIT4 expression." (PMID 35680564, 2022). "Recent data also show that dexamethasone induces a novel epigenetic function for HDAC4, which involves switching on DDIT4 expression in ataxia telangiectasia and, consequently, increasing the protein levels." (PMID 34987545, 2021).
breast tumors (4 papers, 2016 to 2023). "Frequency of structural alteration of DDIT4 found at cbioportal.org, indicate that 0 to 5.1% of primary tumors where DDIT4 was related with the prognostic had mutations, however in breast tumors xenografts, gene amplification occurs in 17.4% elucidating an key role in tumor aggressiveness." (PMID 27294413, 2016).
colon carcinoma (4 papers, 2010 to 2026). "Here, we report that activating transcription factor 4 (ATF4)-dependent REDD1/DDIT4 expression is required for survival of colon tumor cells undergoing endoplasmic reticulum (ER) stress through the modulation of TRAILR2/DR5 gene expression." (PMID 41904147, 2026). "Interestingly, post-surgery levels of PFKFB3, IL1b, HSPA1B and DDIT4 in colon cancer were increased compared to control." (PMID 36733385, 2022). "In GANT61-treated human colon carcinoma cells, novel DNA damage-inducible transcripts DDIT3 (GADD153), DDIT4 (REDD1), DDIT2 (GADD45G), PPP1R15A (GADD34) and ATF3 were significantly up-regulated concomitant with the arrest of cells at G1/S." (PMID 20957031, 2010). "C26 CM upregulated Ddit4, Akt1, and mTOR expression and downregulated phospho-4E-BP1, and phospho-p70S6K in C2C12 compared with CM of CT26, another colon cancer cell line that could not lead to cancer cachexia." (PMID 34175899, 2021).
diabetic nephropathy (4 papers, 2024 to 2025). "By detecting MDA, and noting the activities of SOD and GSH, we have delineated the antioxidative benefits of DDIT4 overexpression, which supports its role in mitigating the pathological damage associated with diabetic nephropathy." (PMID 38567351, 2024). "DDIT4 is an important target of VDR/mTOR/p70s6k/4E-BP1 signaling pathway induced by high glucose in diabetic nephropathy." (PMID 38567351, 2024). "In this study, we explored the mechanism by which DDIT4 influences the polarization phenotypic transformation of macrophages and inflammation through the regulation of mTOR signaling pathway, providing a new mechanism and target for the treatment of diabetic nephropathy." (PMID 40916492, 2025). "The findings are consistent with the results of gene set enrichment analysis (GSEA), indicating that DDIT4 may modulate cellular oxidative stress levels through involvement in the VDR/mTOR/p70s6k/4E-BP1 signaling pathway, thereby ameliorating pathological damage associated with diabetic nephropathy." (PMID 38567351, 2024). "In addition, the expression of green fluorescence in the HG + OE-DDIT4 group was lower than that in the HG + OE-NC group, which confirmed that DDIT4 may participate in the pathogenesis of diabetic kidney disease and improve the pathological damage of diabetic kidney disease." (PMID 38567351, 2024).
myeloma (4 papers, 2018 to 2024). "Previous studies have found that up-regulation of DDIT4 in human myeloma cells inhibits AKT and mTOR signaling and exerts anti-tumor progression effects." (PMID 39593172, 2024). "DDIT4 knockdown inhibited MM cell viability, migration and invasion potential as well as promoted myeloma cells apoptosis under hypoxia." (PMID 36110952, 2022). "Role of DDIT4 in multiple myeloma was confirmed in vivo and in vitro." (PMID 36110952, 2022). "Concerning markers mimicking GC-related side effects, we have shown that REDD1 (DDIT4), an instigator of myeloma cell growth and survival, is decreased by Dex-Spi combination compared to Dex in MM1.S and OPM-2." (PMID 37578563, 2023).
osteosarcoma (4 papers, 2017 to 2023). A usually aggressive malignant bone-forming mesenchymal neoplasm, predominantly affecting adolescents and young adults. "DDIT4 knockout accelerates osteosarcoma cell proliferation, which has also been reported in other types of cancer cells." (PMID 36681687, 2023). "DDIT4 knockout significantly attenuated the inhibitory effects of these NR modulators on osteosarcoma cell growth." (PMID 36681687, 2023). "In particular, the inhibitory effect of the Rev-Erba agonist was almost abolished in DDIT4-knockout cells, indicating that the greatest fold changes in DDIT4 expression caused by the Rev-Erba agonist may be the factor that most strongly contributes to its inhibitory effect on osteosarcoma growth." (PMID 36681687, 2023). "Among the four common target genes of the NR modulators in osteosarcoma cells, DDIT4 has the highest expression level and its expression exhibits greatest fold change after treatment with the modulators." (PMID 36681687, 2023). "DDIT4 knockout rescues the inhibitory effects of the NR modulators on mTOR phosphorylation, downstream S6 phosphorylation and osteosarcoma cell growth, indicating that the NR/DDIT4/mTOR axis plays a key role in the antitumour effects of the NR modulators." (PMID 36681687, 2023). "DDIT4 has been demonstrated to regulate cell proliferation and survival by inhibiting the activity of the mTOR complex, suggesting its critical role in the inhibition of osteosarcoma by the NR modulators." (PMID 36681687, 2023). "Expression data for U2OS cells were also included in the CCLE osteosarcoma cell line data and, although the data was not significant (p = 0.130), DDIT4 showed a positive correlation with PML (Spearman’s r = 0.312), consistent with our observations in this study." (PMID 28332630, 2017).
preeclampsia (4 papers, 2020 to 2025). Preeclampsia is a hypertensive disorder of pregnancy that is characterized by new-onset hypertension with proteinuria presenting after 20 weeks of gestation, and depending on mild or severe forms may initially present with severe headache, visual disturbances, and hyperreflexia. "In addition, the relevance of DDR targets, e.g., DNA damage-inducible transcript 4 (Ddit4), for pathogenic alterations in pregnancy, for instance, of preeclampsia, a pregnancy-specific hypertensive disorder, has also been described." (PMID 32542459, 2020). "Notably, it has been suggested that DDIT4 is critical for normal decidualization and possibly involved in the development of preeclampsia." (PMID 40910216, 2025).
sarcopenia (4 papers, 2016 to 2025). Progressive decline in muscle mass due to aging which results in decreased functional capacity of muscles. "This study uncovers key molecular links between osteoporosis and sarcopenia, highlighting DDIT4, FOXO1, and STAT3 as shared biomarkers." (PMID 41282482, 2025). "Specifically, in the sarcopenia dataset, the CEBPB showed the best diagnostic efficiency for differentiating sarcopenia, while BTG2, CDKN1A, CEBPB, DDIT4, and NFKBIA showed the best-differentiating capability in the OA dataset." (PMID 38962732, 2024). "In the sarcopenia dataset, BTG2 (AUC = 0.867), CDKN1A (AUC = 0.892), CEBPB (AUC = 0.942), DDIT4 (AUC = 0.792), FOXO3 (AUC = 0.900), NFKBIA (AUC = 0.892), ZBTB16 (AUC = 0.808) and ZFP36 (AUC = 0.775) demonstrated better diagnostic efficacy in distinguishing sarcopenia patients from healthy controls." (PMID 38962732, 2024). "Meanwhile, DDIT4, FOXO1, and STAT3 exhibited significant differential expressions in the sarcopenia dataset GSE362." (PMID 41282482, 2025). "Correspondingly, the sarcopenia model showed marked differential expressions of BCL6, DDIT4, FLNA, FOXO1, NFKBIA, PGK1, and STAT3." (PMID 41282482, 2025). "We identified DDIT4, FOXO1, and STAT3 as three central biomarkers that play pivotal roles in the pathogenesis of both osteoporosis and sarcopenia." (PMID 41282482, 2025). "To validate these findings, we examined gene expression across independent datasets and observed consistent differential expression of DDIT4, FOXO1, and STAT3 in both osteoporosis and sarcopenia cohorts, confirming their relevance as shared biomarkers." (PMID 41282482, 2025). "Differential expression analysis in osteoporosis and sarcopenia datasets revealed that seven biomarkers—BCL6, DDIT4, FOXO1, IRS1, NFKBIA, PGK1, and STAT3—were differentially expressed in the independent osteoporosis dataset GSE84500." (PMID 41282482, 2025). "In sarcopenia and OA patients, DDIT4/REDD1 modulates mTOR signalling pathways, contributing to muscle protein synthesis and degradation balance, affecting chondrocyte survival and function under stress conditions, thus playing an important role in muscle atrophy and OA." (PMID 38962732, 2024).
viral infection (4 papers, 2017 to 2024). "Additionally, DEGs related to the response to viral infections, such as DDIT4, CXCR4, EIF5A, TNFAIP3, BCL2, and IRF1, were also upregulated in NBs." (PMID 38440735, 2024).
autism (3 papers, 2024 to 2025). Persistent deficits in social interaction and communication and interaction as well as a markedly restricted repertoire of activity and interest as well as repetitive patterns of behavior. "It has been recently observed that DDIT4 upregulation contributes to autism-like behaviors via a novel ferroptosis mechanism." (PMID 41153391, 2025). "Overexpression of DDIT4 can inactivate the PI3K/Akt pathway and promote neuronal ferroptosis, contributing to the onset of autism symptoms." (PMID 39061976, 2024).
diabetic retinopathy (3 papers, 2021 to 2025). "PF-0423655 was developed for AMD patients by targeting RTP801 (DDIT4), a hypoxia-inducible gene overexpressed in choroidal neovascularization and diabetic retinopathy." (PMID 37430086, 2023).
endotoxemia (3 papers, 2021 to 2023). "DDIT4 enhanced vascular inflammation and permeability in endotoxemia mice, leading to immune cell infiltration, systemic inflammation, caspase-3 activation, and apoptosis." (PMID 34007269, 2021).
heart failure (3 papers, 2019 to 2022). Inability of the heart to pump blood at an adequate rate to meet tissue metabolic requirements. "For example miR-221 is elevated in heart failure patients and the upregulation of miR-221 exerts a protective effect in hypoxia-reoxygenation injury via targeting on Ddit4 and Tp53inp1." (PMID 30934671, 2019). "Previous studies have revealed that miR-221 inhibits autophagy and promotes heart failure by modulating the p27/CDK2/mTOR axis and inhibits hypoxia/reoxygenation-induced autophagy through the DDIT4/mTORC1 and TP53INP1/p62 pathways." (PMID 32477928, 2020).
ischemic stroke (3 papers, 2021 to 2026). A stroke disorder caused by obstruction of blood flow to the brain, due to thrombotic (local blood clot formation) or embolic (due to a blood clot or other material traveling from another site) event. "In summary, this study reveals that lncRNA C2dat2 facilitates autophagy and apoptosis via the miR-30d-5p/DDIT4/mTOR axis in CIRI, improving the understanding of the regulatory mechanism of C2dat2 in CIRI and indicating the potential therapeutic target for ischemic stroke treatment." (PMID 33833132, 2021).